CD14 (CD14 molecule)
Diseases named in the same sentence as CD14 in open-access papers (continued):
Sharing a sentence is not in itself a finding about the gene and the disease.
infection (continued). "Even more relevant is a recent study of infection of CD14+ monocytes by DENV, which upregulated CD16 expression and induced differentiation of B cells into plasmablasts, ultimately increasing IgG secretion." (PMID 30150281, 2018). "Image stream flow cytometry analysis of the same samples demonstrated a frequency of infection of CD14+mLEP+ cells ranging from 30%, 35%, to 25%, when conditioned with no vitamin D, 10-8M 25D3 or 10-7M 25D3, respectively." (PMID 29965969, 2018). "An “intermediate” CD14++CD16+ subpopulation and an activated (CD123+, CX3CR1+, and CD141+) CD14+ monocyte subpopulation associated most strongly with the acute phase of infection when compared against all other identified subpopulations of PBMCs." (PMID 30150281, 2018). "Pregnancy enhanced infection of both lineages in CD14 monocytes, and they found a similar pattern with the African lineage having a higher viral load." (PMID 30072993, 2018). "In 5 additional HIV-infected normal donor cervical explants, we used qRT-PCR to amplify HIV RNA from sorted cervical CD3+CD4+ T cells, CD14+CD11c+ DCs, and CD14+CD11c- macrophages harvested 20 h post-infection." (PMID 30532754, 2018). "Although CD14+CD16+ monocytes expand during the acute phase of infection, community subclustering provides more details on particular sub‐communities that associate with the acute phase." (PMID 30150281, 2018). "Immunofluorescence staining showed that both CD14+/CD16- monocytes and CD14+/16+ PMNs were attached to the Mf at 5 days post-infection by which time significant levels of killing had occurred." (PMID 28045905, 2017). "Since TLR2 and TLR4 are involved in the recognition of Leishmania by neutrophils, it is meaningful that infection with L. major promotes CD14 internalization in neutrophils." (PMID 28187163, 2017). "The PRRSV infection is reported to causes an increase in CD14+ expression throughout the early stage of infection, due to a rise in CD14+ monocytes that differentiate to macrophages and migrate to bronchoalveolar spaces." (PMID 28278192, 2017). "The mean percentages of CD66+, CD14+, and lymphocytes on day 0 of infections were, respectively, 7%, 16%, and 66%." (PMID 27799331, 2017). "Overall, 4 days after infection, the relative proportion of CD14+ cells was significantly higher for the controlled-infection than for the persistent-infection status." (PMID 27799331, 2017). "In this study, using an in vitro infection system, we identified two distinct macrophage subsets, CD14+Siglec-1hiCD4+CD163+MDM and CD14+Siglec-1LoCD4−CD163−MDM." (PMID 29123518, 2017). "Plasmacytoid dendritic cells (pDCs) decreased in frequency in the first two weeks post-infection, whereas mDCs and CD14+CD16- monocytes increased." (PMID 28771605, 2017). "After 4 h of infection, the cells were washed and stained for anti-CD14 to determine the percent of infected cells immediately following infection." (PMID 29358935, 2017). "Two independent infection of CD14+ monocytes with PRVABC59 followed by RNA-seq analysis identified 2662 and 2994 differentially expressed genes in each assay." (PMID 29167459, 2017). "Due to the significant depletion of CD66+ PMN cells on day 0 of infection, the proportions of CD14+ and total lymphocytes were significantly higher than under PMN+ control conditions." (PMID 27799331, 2017). "Our data show that infection of MDMs, MDDCs, dMonWC1+, or dMonWC1neg with Map did not significantly alter surface expression of CD163, CD1b, CD205, CD14, CD172a, CD11b, or CD11c at 48 h post infection." (PMID 28588573, 2017). "At 1 day post FMDV A24 Cruzeiro infection, a statistically significant increase in the expression of IL-10 by CD11c+ DC and CD14+ monocytes was observed." (PMID 27008425, 2016). "A statistically significant 3-fold increase in the percentage of CD14+ monocytes was also observed, which peaked at 5 days post-infection, and the MHC class II expression declined by approximately 70% at day 3 post-infection." (PMID 27008425, 2016).
infection (continued). "Concerning infection with L. braziliensis, data from literature showed that CD14+ monocytes of peripheral blood from CL patients had a decreased expression of CD80 and CD86 following culture with media only or after restimulation with Leishmania antigen." (PMID 27536300, 2016). "The results showed that the infection was Vpx-dependent and that it was the monocytes (CD14+) that had been infected." (PMID 27905985, 2016). "When the infection is resolved, CD14+ DCs leave and tissue-resident CD14− DCs can convert CD127+ ILC1s back into NCR+ ILC3s via secretion of IL-23 and retinoic acid." (PMID 28536374, 2016). "As CHIKV is known to cause cytopathic effects in some cells, we first assessed the viability of the cells following infection and its effect on CD14 expression at 24 hpi." (PMID 27558873, 2016). "Here, we formally demonstrate that challenge with L. monocytogenes induces increased levels of TSHβv synthesis across a range of splenic leukocyte subsets, although the cells that trafficked to the thyroid during infection favored CD14+, Ly6C+, Ly6G+ cells." (PMID 26771831, 2016). "Three days after H9N2 infection, the expression of CD14, TLR4, ERK and JNK protein in the lung tissue was measured." (PMID 27793190, 2016). "The genes encoding CD14 (42.55 fold) and MyD88 (5.54 fold), two proteins involved in signaling trough TLR4, had increased expression levels during infection." (PMID 27982111, 2016). "Specifically, a statistically significant ~50% decrease in the levels of MHC class II expression by CD11c+ cDC, CD11c− cDC, CD4+ MHC class II+ pDC, and CD14+ monocytes was observed at 4 days post-infection, and thereafter recovered to baseline levels." (PMID 27008425, 2016). "By shedding of CD14 from the cell membrane and releasing into circulation during infection status, the LPS–LPB–CD14 complex yields soluble CD14." (PMID 26642970, 2015). "We observed a similar frequency of CD14+CFSE+ cells when the infection was performed with Y or Col cl1.7, after 15 or 72 hours of culture, comparing the different strains." (PMID 26147698, 2015). "Flow cytometry analysis revealed decreased CD14 expression upon lenti-shZFP36L1 infection relative to lenti-ctrl infection." (PMID 26542173, 2015). "The treatment of the cells with tenofovir (TFV), a reverse-transcriptase inhibitor, prevented JR-FL and NL4-3 infection of CD14-derived macrophages and osteoclasts in a dose-dependent manner." (PMID 25809599, 2015). "In fact, during ex vivo infection of primary CD14+ human monocytes, LukAB seems to be the main factor produced by S. aureus responsible for targeting and killing monocytes." (PMID 26069969, 2015). "The expression of HLA-DR on CD14+ cells were significantly lower in the severe infection group compared to the mild group (in acute phase: 34.65±4.88 vs. 10.37±1.69, p<0.001)." (PMID 24664315, 2014). "In response to infection, the amount of CD14 increased in both cell types whereas the expression of the remaining cell surface molecules did not change." (PMID 25270530, 2014). "Using samples of normal human skin we detected productive infection of CD14+ and CD1c+ DCs, LCs and dermal macrophages, which was independent of DC-SIGN expression." (PMID 25474532, 2014). "The infection kinetics were delayed for CD14+ DC and CD1c+ DCs but peaked to similar infection levels as LCs after 36 hrs." (PMID 25474532, 2014). "CD14+ DCs and dermal macrophages were infected at similar rates 24 h after infection, identifying both DCs and macrophages in the skin as potential DENV targets." (PMID 25474532, 2014). "GR1+/Ly6Chigh monocytes and their human CD14++CD16− or CD14++CD16+ counterparts are rapidly recruited to sites of infection or injury and have the potential to differentiate into either inflammatory macrophages or monocyte-derived DC (Mo-DC)." (PMID 25232355, 2014). "Macrophage and CD14+ DCs showed similar infection kinetics but overall infection levels were lower for macrophages compared to CD14+ DCs after 36 hrs." (PMID 25474532, 2014).
infection (continued). "There was a significant increase (p < 0.0001) in the amount of IL-10 produced by ALDCs and CD14+ cells in response to infection with MVA." (PMID 24890724, 2014). "The soluble form of CD14 is also secreted into human milk where it contributes to protection of the neonatal gut from infections." (PMID 24982636, 2014). "In these experiments, the mean infection rates were 28.1% for CD14+ DCs, 39.5% for LCs and 12.5% for CD1c+ DCs." (PMID 25474532, 2014). "Relationship between the MFI of CD14 or CD16 expression on monocytes with infection status and age group." (PMID 25101623, 2014). "Infection of MDBK cells or bovine monocytes (CD14+ cells) with rBRSVΔSH induced significantly more apoptosis than WT rBRSV, 48 h or 24 h after infection, respectively (P<0.0001, P<0.01)." (PMID 24700100, 2014). "RNA-Seq showed that infected CD34 (+) cells did not undergo the same robust HCMV viral gene expression pattern as observed with initial infection of CD14 (+) monocytes." (PMID 23717203, 2013). "We performed chromatin isolation by RNA purification (ChIRP) using biotinylated oligonucleotides specific for RNA4.9 to determine if the transcript interacts with the MIEP region during both latent and initial infection of CD14 (+) monocytes." (PMID 23717203, 2013). "For example, by targeting cells at the site of infection that lack CD14, SchuS4 effectively evades initial detection by host." (PMID 24324751, 2013). "At 14 days post infection of CD14 (+) monocytes, the level of IE1/2 mRNA was undetectable by qPCR, however UL138 and LUNA transcripts were still present (not shown)." (PMID 23717203, 2013). "For RNA-Seq, total cellular RNA from latently infected CD14 (+) monocytes was extracted at 5 and 18 days post infection." (PMID 23717203, 2013). "At 4 days post infection of CD14 (+) monocytes over 130 peaks or nucleosome-depleted regions were elucidated." (PMID 23717203, 2013). "It is important to note that there was very low-level infection of the CD14+CD16+ monocytes, yet there was still exuberant transmigration in response to CCL2." (PMID 23922698, 2013). "Lytic reactivation of latent virus was also performed by incubating latently infected (18 days post infection) CD14 (+) monocytes with IL-6 and re-plating in tissue culture flasks that allowed for cell attachment." (PMID 23717203, 2013). "As expected all transcripts were detected at 1 hr post infection of CD14 (+) monocytes, suggesting that these transcripts are packaged within the HCMV virion (1 hr UV)." (PMID 23717203, 2013). "In order to further verify these results, protein was harvested from HF and CD14+ cells infected at an MOI = 3 at 1day post infection." (PMID 23300789, 2012). "UL81-82ast transcripts were detected in FIX-WT, FIX-ΔLUNA and FIX-Rev infected CD14+ cells throughout the course of infection, including post IL6 induced differentiation." (PMID 23300789, 2012). "Hepatocytes are the major source of most acute-phase proteins, including CD14, which is part of an adaptive response to tissue injury and infection under the control of LPS-signal activated cytokines." (PMID 22511970, 2012). "In the present study, in vitro infection of CD14+ peripheral blood-derived human monocytes with Leishmania major was found to induce differentiation, marked elevation of cellular p53R2 ribonucleotide reductase subunit and R2 subunit expression." (PMID 22496656, 2012). "MDMs used for infection experiments were enriched from buffy coats and the percentage of MDMs after enrichment amounted to around 70% as evaluated after detection of the CD14+ population by means of FACS analysis." (PMID 21629653, 2011). "We determined the capacity of the peptides to inhibit infection of CD14+ monocytes by HIV-1JRFL, a monocyte-tropic HIV-1 strain, using PCR quantification of strong-stop proviral R/U5 long-terminal repeat structures." (PMID 21264298, 2011).
infection (continued). "We then demonstrated that early after infection both monocytes (HLA-DR+CD14+) and DCs (Lin−HLA-DR+CD11c+CD123−) are more prone to undergo apoptosis spontaneously." (PMID 21731488, 2011). "The percentage of BrdU+CD14+CD16+ monocytes was increased after infection at 48hrs post BrdU in both slow and rapid progressors (blue, green, black lines), with a greater increase in the rapid progressors." (PMID 20419144, 2010). "In contrast to slow progressors, a peak in the percentage of BrdU+CD14+CD16− monocytes in rapid progressors appeared at 24hrs post BrdU after infection (blue, green, black lines)." (PMID 20419144, 2010). "A subset of DC (CD11c+CD14− cells) also expresses ERBB3 after treatment with the three infection mimics." (PMID 20668683, 2010). "During natural infection, initiation of the host response begins with CD14 recognition of borrelial lipoproteins and subsequent activation of TLR2." (PMID 20011115, 2009). "Depletion of CD3+, CD14+ or CD56+ cells was performed before infection with delNS1, using magnetic beads labeled with the respective antibodies." (PMID 19125202, 2009). "Mean parasite burden was approximately 2-fold lower (days 6 to 8 post-infection) and 3.6-fold lower (days 9 to 13 post-infection) in CD14-KO mice compared to WT mice." (PMID 19710907, 2009). "These experiments demonstrate that DB and DP contain the same proportion of CD14+ cells while differences in infection profile were observed." (PMID 19543402, 2009). "Results showed that, except for CD14, all known NFκB-regulated genes were significantly up-regulated at 48 hpi during infection, and many of the genes experienced a strong induction from 24 hpi to 48 hpi." (PMID 18811943, 2008). "We then tested the potential of human CD14+ monocytes to facilitate trans infection of TZM-bl cells by isolating monocytes from HIV-1 seronegative subjects and inducing Sn expression with a 48 h pre-treatment of IFN-α." (PMID 18414664, 2008). "In HIV infection, Sn is induced to high levels on CD14+ monocytes shortly after infection, possibly contributing to dysregulation of the immune system." (PMID 18414664, 2008). "Bacterial load and TNF in TLR2-/-, CD14-/- and TLR2-/-/CD14-/- mice was assessed simultaneously in all knockout mice after infection and values in knockout strains were compared to those in wt mice." (PMID 17428319, 2007). "A significantly abbreviated infection course was observed in the CD14 gene knockout mice but hydrosalpinx formation occurred at similar rates between the two groups." (PMID 16995947, 2006). "By 21 days post-infection the mean IFU of 11 remaining culture-positive mice out 18 in the CD14-/- group (2.6 × 103 +/- 7.9 × 103) and 16 remaining culture-positive mice out of 18 in the C57BL/6J wt group (7.3 × 103 +/- 1.1 × 104) was only 65% different." (PMID 16995947, 2006). "Overall, the infection course as assessed by IFU count in CD14-/- mice was significantly abbreviated when assessed by a Kruskal-Wallis analysis of the variance (P < 0.00001)." (PMID 16995947, 2006). "To determine whether ApoBDs (containing ASFV) in the inoculum contribute to the upregulation of CD14 in the early stages of infection, we isolated ApoBDs from the inoculum and infected PAMs with ApoBDs and ASFV particles at the same dose for 3 h." (PMID 40503879, 2025). "Soluble Triggering Receptor Expressed on Myeloid Cells (sTREM-1) and Presepsin (soluble CD14 Subtype) have been demonstrated to be promising emerging biomarkers of infection, given their ability to differentiate new infection from other types of inflammatory responses." (PMID 40523137, 2025). "Neutrophils and Monocyte:CD14+ exhibited high abundance, particularly in the central and upper‐left regions, suggesting localized immune activation in response to infection, while T‐cells, NK cells, and B‐cells showed lower but consistent presence across the tissue." (PMID 40910395, 2025).
infection (continued). "This may explain why the upregulation of bystander CD14 detected under infection conditions is stronger than that induced by incubating with infected supernatant or by exogenously adding ASFV DNA." (PMID 40503879, 2025). "Differentiation of the CD14+ peripheral blood monocytes to macrophages using M-CSF and GM-CSF reduced the influence of TcpC on IL-1β- and TNFα-secretion during an infection with CFT073." (PMID 41310197, 2025). "Presepsin (soluble CD14 subtype, sCD14-ST), a 13 kDa fragment cleaved from monocyte/macrophage surface marker CD14 during bacterial phagocytosis, has emerged as a promising biomarker for early infection detection." (PMID 40647525, 2025). "Total CD68 and CD14 prevalence increased over time after infection in RF-Bcl6no/lo tissues only, suggesting that macrophage accumulation and prolonged inflammation could contribute to sustained TNF-driven immune regulation." (PMID 40924502, 2025). "Among infection biomarkers, an emerging molecule is the soluble CD14 subtype (sCD14-ST), a soluble form of a glycoprotein expressed on the membrane of monocytes and macrophages, released into circulation upon a pro-inflammatory signal against an infectious agent." (PMID 39125464, 2024). "Moreover, the infection-induced expression of Cd14 in EC suggests Toll-like receptor (TLR) activation." (PMID 38767331, 2024). "In both instances of infection, we identified the differentiated upregulation of CD14 as a marker of severity, supported by previous evidence on the inhibition of the upregulation of CD14 as a potential therapeutic against severe infection." (PMID 38892107, 2024). "Platelets are known responders to infection through the TLR4/CD14 immune complex." (PMID 37222974, 2023). "Cytokines, including interleukin-6 (IL-6), interferon-inducible protein-10 (IP-10), and macrophage inflammatory protein 1 (MCP-1), were substantially elevated in blood and were correlated with activated CD4+ T cells, B cells, CD16+CD56+ NK cells, CD14+CD16+ monocytes during infection." (PMID 37033979, 2023). "The infection with Salmonella downregulated the mRNA expression of TLR4 coreceptor CD14." (PMID 38003758, 2023). "Recently, in order to improve the versatility, peripheral monocyte-derived proliferating cells called CD14-ML were generated by the infection of peripheral CD14+ monocytes with retrovirus expressing c-MYC, B-cell lymphoma 2, and BIM1 according to the published method." (PMID 36671815, 2023). "Whereas it is not clearly defined whether L. infantum parasites bind to the membrane CD14 of myeloid cells, a lower level of CL populations was positively correlated with the rate of infection." (PMID 35744760, 2022). "With the infection of larval E. granulosus, there were higher expression levels of many inflammatory factors in splenic B cells, such as Cxcl5, Il1r1, S100a8, S100a9, and CD14, which form a complex network of immune regulation." (PMID 35548052, 2022). "A reduction in circulating immature neutrophils was observed (high CD45+, low CD14+, smaller size), which is closely linked with innate responses to an infection (data not shown)." (PMID 35891560, 2022). "CD14+/ CD16+ monocytes are key players in infection and inflammation." (PMID 36555339, 2022). "We decided to isolate both T-cell subpopulations CD4+ and CD8+ as well as CD20+ B-cells and CD14+ monocytes, since interaction of these cells was hypothesized earlier to be relevant for infection (also see Discussion)." (PMID 35359920, 2022). "In our study, the control ΔM063R infection similar to the wildtype virus did not cause upregulation of CXCL10 in human CD14+ monocytes." (PMID 36103568, 2022). "Most strikingly, there were major changes to CD14+ monocytes after infection." (PMID 35271298, 2022).